XIAP (X-linked inhibitor of apoptosis)
Diseases named in the same sentence as XIAP in open-access papers (continued):
Sharing a sentence is not in itself a finding about the gene and the disease.
colorectal cancer (39 papers, 2010 to 2025). A primary or metastatic malignant neoplasm that affects the colon or rectum. "The X-linked inhibitor of apoptosis protein (XIAP)-mediated ubiquitination of p62 suppresses autophagy, promoting breast/colorectal cancers." (PMID 40643536, 2025). "More importantly, STEAP4 expression correlates with IL-17 level and X-linked inhibitor of apoptosis Protein-XIAP activation in colorectal cancer in humans." (PMID 39518128, 2024). "We previously showed that the expression levels of key apoptotic proteins, including XIAP, can successfully determine benefit from adjuvant chemotherapy and identify high-risk colorectal cancer patients." (PMID 33257690, 2020). "Septin4 is a tumor suppressor protein that promotes cell programmed death in various cell types through specifically antagonizing XIAP (X linked inhibitor of apoptosis), little is known its other novel binding partner and role in colorectal cancer." (PMID 32398959, 2020). "As the members of inhibitor of apoptosis proteins (IAPs), XIAP and Survivin are overexpressed in colorectal cancer, and have been recognized as diagnostic markers and therapeutic targets." (PMID 23758730, 2013). "Together, these results indicated that the disruption of survivin-XIAP complex by Sur-X caused ubiquitination-mediated degradation of survivin and XIAP, and subsequently promoted Caspase 9-dependent intrinsic apoptosis in colorectal cancer cells." (PMID 32381104, 2020). "A prominent example is the overexpression of members of the inhibitor of apoptosis (IAP) protein family, including the X-linked IAP (XIAP) and survivin, which is closely associated with a resistant phenotype of human malignancies, including advanced colorectal cancer." (PMID 31842382, 2019). "In both in vitro and in vivo systems, an IGF-1R antagonist (monoclonal antibody MK-0646) was shown to significantly down regulate X-linked inhibitor of apoptosis (XIAP) protein, which has been shown to be involved in cell survival and inhibition of cell death in colorectal cancer." (PMID 24809702, 2014). "Phosphorylation at Ser4/6 residue of the A1 protein, which is activated by S6K2 kinase in colorectal cancer, controls the cytoplasmic transport and translation of BCL-x(L) and x-linked inhibitor of apoptosis (XIAP)." (PMID 39366930, 2024). "Activation of Akt and NF-κB p65 regulated the survivin, XIAP, Bcl-xL, and Bcl-2 expression in human colorectal cancer cells." (PMID 37069612, 2023). "Mechanistically, it was found that apart from inducing apoptosis by disrupting the survivin-XIAP complex, Sur-X also promoted necroptosis in colorectal cancer cells by interfering with the interaction between XIAP and TAB1." (PMID 32381104, 2020). "In this study we found that PT inhibited the expression of Bcl2, BclxL and XIAP in colorectal cancer cells." (PMID 32703189, 2020). "In colorectal cancer, it was shown that patients with high expression levels of XIAP and cIAP2 have reduced disease-free survival and are more resistant to chemotherapy." (PMID 33257690, 2020). "Less survivin was co-immunoprecipitated with XIAP in colorectal cancer cells treated by Sur-X for 1 h; similarly, the right panel indicated a significant reduction of XIAP in survivin-immunocomplexes in Sur-X-treated cells." (PMID 32381104, 2020). "Despite its seemingly reduced contribution to apoptosis decisions in colorectal cancer, XIAP was still the best singular protein in determining the relative influence of the molecular timer." (PMID 32341447, 2020). "Mechanistically, Sur-X induced Caspase 9-dependent intrinsic apoptosis in colorectal cancer cells by disrupting the survivin-XIAP complex and subsequently destabilizing survivin and XIAP." (PMID 32381104, 2020).
colorectal cancer (continued). "In this study, we aimed to design a peptide that targets the survivin-XIAP complex and elucidate its anticancer mechanisms in colorectal cancer cells." (PMID 32381104, 2020). "HCT116 human colorectal carcinoma cells that consistently overexpress XIAP showed decreased cell proliferation and invasion." (PMID 32994395, 2020). "This study identified XIAP as another E3 ubiquitin ligase of OGT in HCT116 human colorectal carcinoma cells." (PMID 32994395, 2020). "Our published studies have revealed that X‐link inhibitor of apoptosis protein (XIAP), through its RING domain, is able to associate with RhoGDIα and inhibit RhoGDIα SUMOylation, by which XIAP inhibits colorectal cancer cell mobility." (PMID 28846829, 2017). "In colorectal cancer cells high XIAP mRNA levels have been shown to be indicative of tumour differentiation, invasion and progression." (PMID 26071313, 2015). "In summary, our findings support the notion that BV6 mediated degradation of XIAP and cIAP1 results in radiosensitization of colorectal cancer cells via increased apoptosis and impaired DNA DSB repair." (PMID 26383618, 2015). "In the present study, the SMAC mimetic BV6 substantially increased 3D radiation response of three human colorectal cancer cell lines by degradation of cIAP1 and XIAP, thereby enhancing irradiation-induced apoptosis and hampering DNA DSB repair." (PMID 26383618, 2015). "This suggests that the synergistic effect of the combination treatments in colorectal cancer cells was consistent with decreased survival signaling resulting in decreased expression of XIAP." (PMID 23852390, 2013). "In colorectal cancers, the X-linked IAP (XIAP) mRNA levels are significantly higher in primary cancer tissue compared with normal mucosa, and expression was correlated with disease progression and metastasis." (PMID 23720710, 2013). "It has been reported inhibitor of apoptosis proteins, such as XIAP and Survivin are overexpressed in colorectal cancer." (PMID 23758730, 2013). "It was shown that depletion of XIAP in HCT116 colorectal carcinoma cells leads to diminished migration in scratch assays and XIAP-mediated cancer cell migration is RING domain-dependent." (PMID 24008728, 2013). "Similar results were obtained with human colorectal cancer cells in which the XIAP locus was deleted via homologous recombination." (PMID 20067634, 2010). "Importantly, roburic acid inhibited the TNF-induced phosphorylation of IKKα/β, IκBα, and p65, degradation of IκBα, nuclear translocation of p65, and NF-κB-target gene expression, including that of XIAP, Mcl-1, and Survivin, in colorectal cancer cells." (PMID 35222445, 2022). "IAPs (XIAP and survivin) are overexpressed in colorectal cancer and inhibit caspases activity." (PMID 33918514, 2021). "Moreover, it was confirmed that Sur-X indeed disrupted the formation of survivin-XIAP complex in colorectal cancer cells." (PMID 32381104, 2020). "As the first peptide that targets the survivin-XIAP complex, Sur-X was proved to be able to interfere with survivin-XIAP interaction, promote ubiquitination-mediated degradation of survivin and XIAP, and hence induce Caspase 9-dependent intrinsic apoptosis in colorectal cancer cells." (PMID 32381104, 2020). "Since the interactions between survivin and XIAP were decreased significantly upon the treatment of Sur-X for only 1 h, we speculated that Sur-X might induce apoptosis in colorectal cancer cells by destabilizing survivin and XIAP." (PMID 32381104, 2020). "Moreover, the ubiquitination levels of both survivin and XIAP were enhanced in colorectal cancer cells with the treatment of Sur-X." (PMID 32381104, 2020).
colorectal cancer (continued). "Survivin and XIAP are two important members of the inhibitor of apoptosis protein family and have been considered as potential targets for cancer treatment due to their overexpression in large variety of cancers including colorectal cancer." (PMID 32381104, 2020). "Previous own data further revealed 3D radiosensitization in a panel of colorectal cancer cells upon siRNA-mediated attenuation of XIAP and/or Survivin in line with an increased γH2AX foci detection following single XIAP and Survivin or double knockdown (unpublished results)." (PMID 26383618, 2015). "XIAP and Survivin may inhibit activation of Caspases, downregulation of XIAP and Survivin could sensitize colorectal cancer cell to drug induced apoptosis." (PMID 23758730, 2013). "Therefore, we hypothesized that interfering with the interaction between survivin and XIAP may be a promising approach for colorectal cancer treatment." (PMID 32381104, 2020). "Therefore, we inferred that blocking the interactions between survivin and XIAP might be a promising therapeutic strategy in colorectal cancer." (PMID 32381104, 2020). "Therefore, we speculated that the peptide targeting the survivin-XIAP complex might be a promising therapeutic strategy for colorectal cancer treatment." (PMID 32381104, 2020). "Treatment with NCTD decreased the expression of XIAP in HCT116 and HT-29 cells, further confirming that NCTD induces apoptosis in colorectal cancer cells." (PMID 40003916, 2025). "Many studies found miR-377 acts as a tumor suppressor by targeting EGR1, SGK3, XIAP ZEB2 CUL4A and others in lung tumorigenesis, cervical carcinoma, colorectal cancer and ovarian cancer." (PMID 35741709, 2022). "On the other hand, in colorectal cancer HCT116 cells, C6 inhibited the activation of ERK1/2, cyclin-dependent kinase 1, and AKT, down-regulated the protein level of XIAP, and up-regulated pro-apoptotic Bax and caspase-3/7 expression." (PMID 35408786, 2022). "In colorectal cancer, miR-377-3p suppressed Wnt/ß-catenin signaling by directly targeting ZEB2 and XIAP, thus inhibiting the tumor progression." (PMID 35057851, 2022). "All these results indicated that Sur-X promoted necroptosis by interfering with the interactions between XIAP and TAB1 and subsequently destabilizing TAK1 to alleviate the inhibition of TAK1 on necroptosis in colorectal cancer cells." (PMID 32381104, 2020). "XIAP was also phosphorylated in mitotic HCT116 and DLD1 human colorectal cancer cells with a very similar pattern of phosphorylated forms." (PMID 27927753, 2017). "Our recent studies show that XIAP upregulates cyclin D1 via its C-terminal RING domain to promote bladder cancer cell growth and enhances colorectal cancer cell motilities through inhibiting the RhoGDIα SUMOlation at the lys-138 site." (PMID 28057023, 2017). "In this paper, we demonstrate that the apoptosome molecular timer acts synergistically with XIAP in the prevention of apoptosis execution and that simulating these processes can contribute to correctly prognosticate patient survival in stage III colorectal cancer." (PMID 32341447, 2020). "However, when protein synthesis in colorectal cancer cells was blocked by CHX, Sur-X was found to promote the degradation of survivin and XIAP." (PMID 32381104, 2020). "Moreover, our recent study reveals that XIAP directly binds to E2F1 via N-terminal BIR domains and enhances E2F1 transcriptional activity, which subsequently promotes colorectal cancer cell growth." (PMID 28057023, 2017). "Our studies have identified miR-587 as a potential target for drug resistance in colorectal cancer and suggested that modulating the PPP2R1B (PP2A)/pAKT/XIAP axis may have benefits against drug resistance." (PMID 26247730, 2015).
colorectal cancer (continued). "We demonstrate that combinations of TRAIL and PI-103 or 17-AAG were synergistic or additive and induced increased apoptosis in TRAIL-resistant human colorectal cancer cells with the simultaneous inhibition of the activity or expression of ERBB2, AKT, IKKα and XIAP." (PMID 23852390, 2013). "In addition, roburic acid induced the apoptosis of colorectal cancer cells by promoting the cleavage of PARP, Caspase3, Caspase7, and Caspase9, as well as downregulating the levels of the antiapoptotic proteins Bcl-2, Bcl-xL, XIAP, Mcl-1, and Survivin." (PMID 35222445, 2022). "Furthermore, the analysis by GEPIA suggested that among other IAPs apart from survivin, the expression of XIAP was also higher in colorectal cancer tissues, although with no statistical significance." (PMID 32381104, 2020). "The expression of NF-κB-dependent anti-apoptotic genes (XIAP, Bcl-xl, and Bcl-2) was also shown to be downregulated, suggesting that miR-15b-5p negatively regulates NF-κB1 and IKK-α, resulting in the suppression of NF-κB-dependent survival proteins in colorectal cancer." (PMID 28646148, 2017). "Online databases Oncomine and GEPIA were used to compare the expression of IAPs (NAIP, BIRC2, BIRC3, XIAP, BIRC5/survivin, BIRC6 and BIRC7, no data on BIRC8 was available) between colorectal cancer and normal tissues." (PMID 32381104, 2020).
inflammatory bowel disease (37 papers, 2013 to 2026). A spectrum of small and large bowel inflammatory diseases of unknown etiology. "X-linked inhibitor of apoptosis protein (XIAP) deficiency causes refractory inflammatory bowel disease." (PMID 38191507, 2024). "One patient with XIAP deficiency had mixed chimerism and inflammatory bowel disease controlled with adalimumab therapy." (PMID 36456809, 2023). "XIAP deficiency (X-linked inhibitor of apoptosis) is clinically characterized by sHLH, inflammatory bowel disease, and splenomegaly." (PMID 37446301, 2023). "Development of an inflammatory bowel disease (IBD)-like phenotype occurs in 25% to 30% of patients with XIAP deficiency and is associated with poor outcomes." (PMID 37205951, 2021). "Phenotypically it highly resembles XLP1, with the addition that splenomegaly is often the first presenting manifestation and that XIAP deficiency is associated with inflammatory bowel disease." (PMID 34867986, 2021). "Inflammatory bowel disease (IBD) is also a prevalent phenotype affecting 25–30% of XIAP-deficient patients, which has been reported in many other countries." (PMID 31754776, 2020). "High blood concentrations of IL-18 are also found in patients with allergic diseases, including bronchial asthma, atopic dermatitis, inflammatory bowel disease, and the X-linked inhibitor of apoptosis (XIAP) deficiency." (PMID 30992532, 2019). "There are, however, certain rare forms of IBD, particularly in pediatric patients, that can be classified as monogenic, which are caused by mutations in single genes like IL10RA, IL10RB, or XIAP genes, and often present as very early-onset inflammatory bowel disease (VEO-IBD)." (PMID 40611267, 2025). "The spectrum of pathologies associated with XIAP mutations suggests that defects in XIAP function might contribute to additional disorders characterized by deregulated immune responses such as inflammatory bowel diseases." (PMID 23818254, 2013). "Subsequent reports demonstrated the assay's usefulness in diagnosing inflammatory bowel disease (IBD) cases with novel XIAP mutations." (PMID 31396234, 2019). "Mutations in the X-linked inhibitor of apoptosis (XIAP) gene have been described in several patients suffering from IBD and, in particular, with very early-onset inflammatory bowel disease (VEOIBD) features." (PMID 29312354, 2017). "Monogenic IBD typically manifests as very early onset(very early onset inflammatory bowel disease (VEO-IBD)), caused by rare pathogenic variants in genes such as IL10R and X-linked inhibitor of apoptosis protein (XIAP)." (PMID 41495287, 2026). "X-linked inhibitor of apoptosis protein (XIAP) deficiency is a severe immunodeficiency with clinical features including hemophagocytic lymphohistiocytosis (HLH) and inflammatory bowel disease (IBD) due to defective NOD2 responses." (PMID 36329240, 2023). "Furthermore, XIAP deficiency was associated with a particular inflammatory pattern consisting of recurrent fever, uveitis, and inflammatory bowel disease (IBD)." (PMID 37426667, 2023). "XIAP deficiency is associated with inflammatory bowel diseases (IBD); however, this case report may extend the spectrum of chronic GI diseases associated with this immunodeficiency." (PMID 36675441, 2023). "Inflammatory bowel disease (IBD) is a clinical diagnosis that often brings patients with WAS, CVID, X‐linked inhibitor of apoptosis (XIAP) deficiency, NEMO deficiency, CGD, or XLA to medical centers." (PMID 37102642, 2023). "X-linked inhibitor of apoptosis (XIAP) deficiency with XIAP/BIRC4 gene mutations is a primary immune deficiency clinically characterized by HLH, inflammatory bowel disease, and splenomegaly." (PMID 36211331, 2022). "XIAP deficiency is a rare IEI, and it is characterized by recurrent hemophagocytic lymphohistiocytosis and refractory inflammatory bowel disease (IBD) similar to Crohn’s disease." (PMID 35155270, 2021).
inflammatory bowel disease (continued). "XIAP also plays a role in pathogen infection, inflammatory bowel disease, and some hematological diseases." (PMID 34025452, 2021). "X-linked inhibitor of apoptosis (XIAP) deficiency is a rare primary immunodeficiency disease characterized by haemophagocytic lymphohistiocytosis, recurrent splenomegaly and inflammatory bowel disease (IBD)." (PMID 32305064, 2020). "XIAP deficiency, caused by XIAP gene mutations, leads to a rare primary immunodeficiency disease with clinical phenotypes including hemophagocytic lymphohistiocytosis (HLH), lymphoma, splenomegaly, hypogammaglobulinemia and inflammatory bowel disease (IBD)." (PMID 37479963, 2023). "Furthermore, genetic variants in interleukin-10 (IL-10), IL-10 receptor(IL-10R), X-linked inhibitor of apoptosis protein (XIAP), and forkhead box P3 (FOXP3) have been linked to very early-onset inflammatory bowel disease (VEOIBD)." (PMID 34956195, 2021). "X-linked inhibitor of apoptosis (XIAP) deficiency is a rare primary immunodeficiency with a broad spectrum of clinical manifestations, including susceptibility to hemophagocytic lymphohistiocytosis (HLH), inflammatory bowel disease (IBD), hypogammaglobulinemia, and severe infections." (PMID 38912075, 2024). "The dynamics associated with these hotspots are crucial for the interaction between RIPK2 and XIAP, a key element in NOD1/2-mediated immune responses, with implications in inflammatory bowel disease and other conditions." (PMID 39190764, 2024). "XIAP deficiency is a rare primary immunodeficiency and characterized by immune dysregulation and a broad spectrum of clinical manifestations, including haemophagocytic lymphohistiocytosis (HLH) and inflammatory bowel disease (IBD), etc." (PMID 37407577, 2023). "XIAP deficiency was first described in 2006 and is associated with a variety of disease manifestations, including recurrent haemophagocytic lymphohistiocytosis (HLH), inflammatory bowel disease (IBD), hypogammaglobulinemia, severe and/or recurrent infections, splenomegaly, and cytopaenias." (PMID 34222142, 2021). "The Genomics England R15 primary immunodeficiency and monogenic inflammatory bowel disease gene panel of 429 genes did not reveal any pathogenic variants, including genes known to be associated with high IL-18 levels and inflammation such as NLRC4 or XIAP." (PMID 39458007, 2024). "None of inflammatory bowel disease (IBD) has been reported among XIAP-deficient patients in our center; however, whether Chinese XIAP-deficient patients will develop colitis in the future warrants further investigation." (PMID 31754776, 2020). "The clinical features of XIAP deficiency are characterized by susceptibility to Epstein–Barr virus (EBV) infection, recurrent HLH with/without EBV, splenomegaly, inflammatory bowel disease (IBD), and hypogammaglobulinemia." (PMID 35958573, 2022).